WDR5 (WD repeat domain 5)
Diseases named in the same sentence as WDR5 in open-access papers (continued):
Sharing a sentence is not in itself a finding about the gene and the disease.
neurodevelopmental disorder (3 papers, 2019 to 2023). A behavioral and cognitive disorder with onset during the developmental period that involves impaired or aberrant development of intellectual, motor, or social functions. "In conclusion, by identifying and characterizing individuals with rare de novo missense variants in WDR5, we suggest the presence of a novel Mendelian neurodevelopmental disorder." (PMID 36408368, 2023). "All in all, we define a neurodevelopmental disorder associated with missense variants in WDR5 and a broad range of features." (PMID 36408368, 2023). "Our report is the first to associate heterozygous variants of WDR5 with a neurodevelopmental disorder, therefore further evidence of causative variants in children with CAS or a related phenotype will be important to confidently implicate this gene." (PMID 29463886, 2019). "This may be an instrumental next step in responding to WDR5-associated neurodevelopmental disorders if future research goes in similar directions as ARID1B and KANSL1." (PMID 36743289, 2022). "WD Repeat Domain 5, a member of the WD-40 group of proteins, is considered a highly conserved molecule and involved in multiple pathologies ranging from cancer to neurodevelopmental disorders as well as neurodegenerative diseases such as Huntington’s disease." (PMID 36743289, 2022).
blood cancer (1 paper, 2021). "WDR5 plays an essential role in protein expression in MLL1 blood cancer." (PMID 34452553, 2021).
muscular disorders (1 paper, 2025). "Understanding WDR5's interactome and regulatory networks could provide novel insights into muscle regeneration, stem cell dynamics, and potential therapeutic strategies for muscular disorders and regenerative medicine." (PMID 41084152, 2025).
WDR5 also shares sentences with these, for which no sentence is quoted: sarcoma (2 papers); Alzheimer disease (1); apraxia (1); atherosclerotic heart disease (1); chronic lymphocytic leukemia (1); Coffin-Siris syndrome (1); Colon (1); colon adenocarcinoma (1); conotruncal heart defect (1); developmental delay (1); endometrial cancer (1); endometriosis (1); esophageal cancer (1); esophageal squamous cell carcinoma (1); Ewing sarcoma (1); hematopoietic cancer (1); Joubert syndrome (1); Kleefstra syndrome (1); Koolen-de Vries syndrome (1); lung adenocarcinoma (1); metastatic disease (1); microcephaly (1); Myocardial fibrosis (1); non-small cell lung carcinoma (1); oral cancer (1); osteosarcoma (1); ovarian carcinoma (1); pancreatic adenocarcinoma (1); rhabdomyosarcoma (1); squamous cell carcinoma (1).
A further 3 diseases each share a sentence with WDR5 in 1 paper.